MAP2K7 (mitogen-activated protein kinase kinase 7)
Diseases named in the same sentence as MAP2K7 in open-access papers (continued):
Sharing a sentence is not in itself a finding about the gene and the disease.
cancer (280 papers, 2000 to 2026). A tumor composed of atypical neoplastic, often pleomorphic cells that invade other tissues. "Loss of the JNK pathway, particularly MAP2K7, impaired the anti-proliferative and pro-senescent response of cancer cells to endocrine therapy and CDK4/6 inhibition." (PMID 40826108, 2025). "While there has been interest in inhibiting JNK due to its involvement in inflammatory processes and cancer, there is increasing focus on developing MAP2K7 inhibitors to enhance specificity when MAP2K7 activation is associated with disease progression." (PMID 39717752, 2024). "Previous studies have linked molecular changes in MAP2K7 to cancer and an upregulation of the MAPK/JNK signalling pathway." (PMID 37692064, 2023). "This is not the first instance where changes in the molecular events of the MAP2K7 gene have been associated with cancer." (PMID 37692064, 2023). "The 8-mRNAsi based prognostic model in our signatures includes RGS16, LYVE1, hnRNPC, ANP32A, AIMP1, ZNF66, PIK3R3, and MAP2K7, in which several genes have been reported to be linked with stemness features or be involved in cancer progression." (PMID 33329703, 2020). "The results indicate a relationship between increased MAP2K7 gene expression and the occurrence of cancer metastases in the liver in patients with CRC." (PMID 41515982, 2025). "The MAP2K7 gene, which codes for the MKK7 protein, plays an important part in the initiation, development, and progression of cancer." (PMID 38419894, 2024). "In recent years, significant efforts have been dedicated to developing novel MAP2K7 inhibitors for use as research tools and potential new cancer treatments." (PMID 39717752, 2024). "Despite some progress, further research is needed to fully comprehend the role of MAP2K7 in cancer and assess the potential use of kinase inhibitors in cancer therapy." (PMID 39717752, 2024). "In this study, we discovered that RIPK2 interacts with six protein kinases: MKK7 (MAP2K7), DNA-PKcs (PRKDC), RSK2 (RPS6KA3), MST4 (STK26), MEK2 (MAP2K2), and CSK (CSK), many of which were implicated in cancer metastasis." (PMID 35115556, 2022). "JNK inhibitors were used first to target the MAP2K7 pathway because many small molecules have been studied in clinical trials for applications in inflammatory disorders and cancer." (PMID 34504651, 2021). "In fact, MAP2K7 transcripts are elevated in most cancer cell line types represented in the Cancer Cell Line Encyclopedia." (PMID 34504651, 2021). "MAP2K7 is known to activate JNKs, which may promote proliferation and resistance to cellular stress in cancer cells." (PMID 41515982, 2025). "A clearer understanding of MAP2K7's role in normal and disease states and the development of small-molecule inhibitors will facilitate the exploration of potential clinical applications in cancer and other diseases." (PMID 39717752, 2024). "Several candidates identified in our experiment, either in CuCl2-or CuCl2 and LA-treated groups, are directly involved in cancerogenesis (such as MEMO1, ATOX1, L1CAM, RABGGTA, MAP2K7 and others, and may be of potential interest for anti-cancer research." (PMID 39290994, 2024). "This review examines the role of MAP2K7 in cancer and the development of small-molecule inhibitors." (PMID 39717752, 2024). "Furthermore, numerous other protein kinases implicated as driver genes in various other cancers were identified here, including NTRK3 and MAP2K7." (PMID 33572851, 2021). "Moreover, it is known that activated MAP2K7 enhances the proliferation, metastasis and progression of cancer." (PMID 32776229, 2020). "Finally, a study of an upstream regulator indirectly links MAP2K7 to cancer." (PMID 39717752, 2024). "After assessing the mRNA expression levels of selected genes, we assessed the expression of MAP2K4, MAP2K7, MAPK8, and MAPK9 proteins in cancer and normal colon tissue using images from the Human Protein Atlas." (PMID 41515982, 2025).
cancer (continued). "Since JNK is involved in cellular processes targeted in cancer and JNK is the sole substrate of MAP2K7, MAP2K7 emerges as a new potential therapeutic target." (PMID 39717752, 2024). "MAP2K7 and MAPK8 may promote disease progression and metastasis, whereas MAPK9 and MAP2K4 may be more protective at certain stages of cancer development." (PMID 41515982, 2025).
infection (17 papers, 2009 to 2025). The state of being infected such as from the introduction of a foreign agent such as serum, vaccine, antigenic substance or organism. "Many downstream effector genes such as Interleukin-1 receptor-associated kinase 1 (Irak1), Transcription factor (Jun), Mavs [Ips-1], Mitogen-activated protein kinase kinase 7 (Map3k7[Tak1]) were downregulated during infection." (PMID 36851549, 2023). "At 48 hr of infection, the levels of MAP2K7 in Ad-MAP2K7-infected, but not Ad-GFP infected, Map2k7(−/−) cells were similar to or even higher than those in the WT cells." (PMID 19654923, 2009). "In addition, genes that targeted kinases (MAP2K7, MAP4K4 and MAPK14) were downregulated in the first 15 min of CHIKV infection, although MAP2K7 and MAP4K4 were subsequently found to be upregulated after 30 min and 120 min of infection." (PMID 23409203, 2013). "Our microarray data revealed a major suppression of several components of the JNK pathway (MAP4K2, MAP3K5, MAP2K7 and MAP2K4), with the exception of JNK2 (also known as MAPK9), which was increased at 24 h; the other two Jun kinases, JNK1 and JNK3, were not significantly affected by infection." (PMID 28480889, 2017).
psychiatric disorder (2 papers, 2017). A disorder characterized by behavioral and/or psychological abnormalities, often accompanied by physical symptoms. "Overall, Map2k7 haploinsufficiency causes behavioural alterations in accordance with those seen in psychiatric patients carrying out similar tasks, along with molecular changes relevant to cognition and psychiatric disorders." (PMID 27774567, 2017).
MAP2K7 also shares sentences with these, for which no sentence is quoted: pancreatic cancer (29 papers); fibrosarcoma (21); metastatic melanoma (21); ovarian carcinoma (21); non-small cell lung carcinoma (20); plexiform neurofibroma (12); osteosarcoma (10); cardiac hypertrophy (9); sarcoma (9); neuroblastoma (8); pancreatic ductal adenocarcinoma (8); bladder cancer (7); cutaneous melanoma (7); Insulin resistance (7); lung adenocarcinoma (7); thyroid cancer (6); uveal melanoma (6); viral infection (6); acute myeloid leukemia (5); Cerebral ischemia (5); low grade glioma (5); metastatic disease (5); neurofibroma (5); retinopathy (5); Arthritis (4); brain tumor (4); cervical carcinoma (4); lymphoma (4); oral cancer (4); schwannoma (4).
A further 190 diseases each share a sentence with MAP2K7 in 3 papers or fewer.